IGF1 (insulin like growth factor 1)
Diseases named in the same sentence as IGF1 in open-access papers (continued):
Sharing a sentence is not in itself a finding about the gene and the disease.
Insulin resistance (continued). "In cell models, CYP17A1 was found to be involved in glucose metabolism by increasing glucose intake and utilization, through activating IGF1/mTOR/HIF1-α signaling way, which was consistent in CYP17A1 knockout mice with impaired glucose tolerance and insulin resistance." (PMID 37370070, 2023). "Other studies have also shown a relationship of the amount of adipose tissue, peripheral insulin resistance, and the level of IGF-1, as adipose tissue is one of the sources of IGF-1, and insulin resistance accompanying obesity increases the level of this protein." (PMID 37373743, 2023). "Prevention of diabetes and treatments targeting abnormal glucose metabolism, IGF-1/IGF-1R signaling axis, and insulin resistance may provide novel opportunities to improve prognosis and delay the lethal metastases of intraocular malignancies." (PMID 36003786, 2022). "In addition, BS21 lowered the circulating glucose and IGF-1 levels which were beforehand increased by HFD-induced obesity, thereby suggesting that BS21 can regulate insulin resistance." (PMID 35276805, 2022). "Elevated androgen levels not only lead to associated clinical features manifested as hirsutism and acne but are also responsible for elevated insulin-like growth factor-1 (IGF-1) levels, leading to metabolic abnormalities (insulin resistance, dysglycaemia and dyslipidaemia)." (PMID 35265039, 2022). "We see it as a limitation of our study that we do not have data on fetal insulin resistance, estrogen, IGF-1, and leptin." (PMID 35184136, 2022). "OB people also had lower IGF1 (P < 0.05), and 25OHD (P < 0.001) and higher PTH (P < 0.05), insulin, glucose, homeostatic model assessment for insulin resistance (HOMA-IR) (all P < 0.001) than NW people." (PMID 36173650, 2022). "In the present study, we found that overexpression of GH did not lead to insulin resistance but reduced serum glucose concentration and increased hepatic expression level of igf-1 and glycolysis pathways, which decreased glycogen content in the liver." (PMID 36561570, 2022). "In these models, impairment of insulin/IGF-1 signaling did not necessarily lead to systemic insulin resistance." (PMID 36198696, 2022). "It seems that while the negative feedback of the STAT3 signaling delays the insulin/IGF-1-induced aging process, it nonetheless elicits insulin resistance and diabetes." (PMID 34476533, 2021). "Downregulation of miR-190b by directly targeting IGF-1 and ADAMTS9 could regulate lipid metabolism and insulin signaling pathway in vitro and could reduce the hepatic steatosis and insulin resistance in vivo." (PMID 33768092, 2021). "Moreover, the results of multiple regression analysis showed that independent correlation between insulin resistance is represented by WBISI and IGF-1 SDS after adjusting for other traditional cardiovascular disease risk markers." (PMID 34485526, 2021). "As in our research, regardless of age, BMI, eGFR, HOMA-IR negative related to IGF-1 and positively related to BALP, we assumed that it is possible insulin resistance decreases the bone turnover, raises the risk of osteoporosis." (PMID 35223754, 2021). "The Janus kinase (JAK)/STAT3 pathway as well as the activation of STAT3 through AKT kinase and mTOR are the important insulin/IGF-1-stimulated, STAT3-mediated signaling pathways which are able to control immunosuppression, immunosenescence, and insulin resistance." (PMID 34476533, 2021). "After treatment of acromegaly, insulin resistance decreased and glucose homeostasis improved, even when IGF-1 normalization was not achieved." (PMID 32458292, 2020). "In addition, given its capacity to increase the insulin-like growth factor-I (IGF-1), cepharanthine was shown to lower blood glucose and decrease insulin resistance." (PMID 32650482, 2020).
Insulin resistance (continued). "Increasing IGF-1 by augmenting the GH dose in the HD group significantly increased insulin resistance compared to baseline (1.12 vs. 0.79, p=0.01), whereas no significant change was detected during decreased levels of IGF-1 (0.74 vs. 0.80, p=0.24)." (PMID 33633687, 2020). "It has been suggested that IGF-1 excess decreases NO production via induction of insulin resistance, but this relation has not been observed in all studies." (PMID 32458292, 2020). "In particular, GH secretion, insulin-like growth factor-1 levels, and the magnitude of insulin resistance have not been measured, which limits mechanistic interpretations of our findings." (PMID 31766118, 2019). "In addition, increased expression of insulin-like growth factor-1 (IGF-1) and IGF-binding proteins has been observed in obesity as a result of insulin resistance and increased circulating estrogen." (PMID 31475003, 2019). "Hyperinsulinemia, especially in the presence of insulin resistance, may promote cancer cell growth either through insulin receptor or IGF-1 receptor, or via increased bioavailability of free IGF-1 by inhibiting the expression of IGF binding proteins." (PMID 31518336, 2019). "Moreover, the correlation between IGF1/IGFBP3 and severity of NAFLD retains significance, after adjustment for age, gender, race/ethnicity, homeostasis model assessment for insulin resistance (HOMA-IR) and adiposity." (PMID 29702590, 2018). "The incorporation of somatotropic axis hormone supplementation, particularly low dose IGF-1, as a pharmacological therapy in patients with the triad of NAFLD, insulin-resistance and sarcopenia could be promising." (PMID 29724029, 2018). "The aim of this study was to analyse and compare the effects of GH and IGF-1 supplementation in liver, adipokines and muscular tissue in an NAFLD experimental model that resembles features of early NAFLD stages including obesity and insulin resistance." (PMID 29724029, 2018). "The lower ratio of IGF-1/IGFBP-3 was also observed in patients with NAFLD, suggesting that a decrease in circulating free IGF-1 levels may account for exacerbation of insulin resistance and advanced hepatic steatosis." (PMID 29342898, 2018). "Moreover, when considering insulin resistance in PCOS, further evaluation on the interaction between IGFBP-1 and IGF-1 is required for a better understanding of the pathophysiology." (PMID 30775682, 2018). "Interestingly, PHLDA1 is induced by IGF-1 and insulin upregulates IGF-1 receptors in conditions with insulin resistance, as in PCOS." (PMID 28068351, 2017). "High levels of circulating insulin due to insulin resistance or insulin treatment also result in reduced insulin-like growth factor binding protein (IGFBP), leading to increased insulin-like growth factor 1 (IGF-1), which has more potent anti-apoptotic and mitogenic effects than insulin." (PMID 29238337, 2017). "On the model of type II diabetes characterized by insulin resistance, IGF-1 resistance in HD may be approached by direct IGF-1 administration or indirectly by increasing IGF-1 plasma levels." (PMID 27627435, 2016). "In contrast to its negative effects on growth and proliferation, reduced IGF-1 signaling has been reported to positively correlated insulin resistance." (PMID 24586785, 2014). "Physical inactivity and a Western-pattern diet shift energy balance leading to hyperinsulinaemia, high insulin-like growth factor 1 (IGF-1) levels and insulin resistance which stimulate growth and inhibit apoptosis of micro-metastases leading to cancer recurrence and mortality." (PMID 23688320, 2013). "In the whole cohort, the change in insulin resistance between baseline and after 1 year of study medication was inversely correlated with changes in IGFBP1 (r=−0.28; P=0.001) and directly correlated with changes in IGF1 (r=0.22; P=0.01)." (PMID 24026893, 2013).
Insulin resistance (continued). "Furthermore, there was correlation with testosterone (r=−0.306, P<0.01) and other androgens, homeostasis model of assessment insulin resistance (HOMA IR; r=0.456, P<0.001), VO2 max (r=−0.262, P=0.04), IGF1 (r=−0.297, P=0.01), and CRP (r=0.302, P=0.01)." (PMID 24148221, 2013). "A Cox regression model was applied to test for the associations between cancer mortality and fasting serum glucose, insulin, glycosylated hemoglobin (HbA1c), C-peptide, insulin like growth factor (IGF-1), IGF binding protein 3 (IGFBP3) and estimated insulin resistance." (PMID 23405181, 2013). "In addition, other cell culture models of insulin resistance, such as osmotic stress or chronic exposure to insulin or IGF1 (IGF-1), have been shown to promote degradation of IRS2 in NIH3T3 cells." (PMID 19007436, 2008). "Interestingly, BRCA1/2 mutation carriers often have very low or very high levels of insulin-like growth factor 1 (IGF-1) in the serum compared to non-carriers, which is associated with an increased risk for insulin resistance." (PMID 39621070, 2025). "Therefore, more comprehensive clinical indicators such as insulin-like growth factor 1 (IGF-1) and estradiol should be investigated to better illustrate the relationship between endometrial polyps and insulin resistance, which is also a limitation of this study." (PMID 38909214, 2024). "Moreover, miR-133a regulates insulin-like growth factor 1 (IGF-1) in the heart and regulates the etiology of insulin resistance; it was found that IGF-1 depletion reduces the phosphorylation of GATA binding protein 4, glucose transporter-4 (GLUT4), and protein kinase B (AKT)." (PMID 39468643, 2024). "However, considering that insulin resistance indices are correlated with IGF-1 and not with GH in the majority of studies, the etiology of predominance of GH effect appears to be more complicated." (PMID 36882643, 2023). "Insulin resistance is ascribed to the direct, diabetogenic effects of growth hormone (GH), which prevail over the insulin-sensitizing effects of insulin-like growth factor 1 (IGF-1), probably due to higher glucometabolic potency of GH, IGF-1 resistance, or both." (PMID 36882643, 2023). "Obesity is a significant risk factor for endocrine and cardiovascular chronic diseases, and recent studies have demonstrated that low IGF-1 levels in obese children are closely related to nonalcoholic fatty liver disease, low high-density lipoprotein cholesterol, and insulin resistance." (PMID 37111069, 2023). "Interestingly, we observed that IGF-1 levels correlated differently with metabolic and insulin resistance-related variables in subjects with or without MetS." (PMID 37106164, 2023). "Furthermore, other studies have highlighted a non-linear (i.e., U-shaped) relationship between insulin resistance and IGF-1 levels in patients with MetS." (PMID 37106164, 2023). "Insulin resistance and hyperglycemia as features of T2DM have a detrimental effect on cognitive abilities, since insulin and insulin-like growth factor, also called somatomedin C (IGF-1), play an important role in cognitive ability, neural function, and development." (PMID 35563031, 2022). "Wu found that BSJPHX principle could significantly improve the clinical symptoms of TCM in patients with T2DOP, effectively reduce blood glucose and glycosylated hemoglobin, fasting insulin level and insulin resistance index, and improve BMD and serum IGF-1, IRS-1, IRS-2 levels." (PMID 33761702, 2021). "However, the authors concluded that the myotrophic effect of IGF-1 might be adversely affected by insulin resistance, so therapeutic interventions for dysregulated glucose metabolism in SMA should target insulin resistance." (PMID 33339220, 2020). "Next to the change in neurogenic activity, decrease in IGF-1 level in our study led to a decreased contribution of the endothelial activity to the vasomotion, which seemed to be independent of change in waist circumference or insulin resistance." (PMID 33633687, 2020).
Insulin resistance (continued). "Moreover, insulin-resistance reduces IGF-1 blood levels, for negative balance and spill-over effect between hormones." (PMID 32033349, 2020). "The patients of acromegaly with normal glucose tolerance could maintain euglycaemia even in the face of significantly increased insulin resistance due to the stimulatory/cytotrophic effect of elevated GIP and GH/IGF-1 on β-cells and/or as a part of innate β-cell reserve." (PMID 30948746, 2019). "In addition, exogenous IGF-1 has been shown to lower serum glucose levels not only in healthy individuals, but also in those with insulin resistance." (PMID 30302116, 2018). "Emphasis on intake of non-refined plant-based foods may improve insulin resistance and decrease circulating levels of insulin-like growth factor-1 (IGF-1), a proproliferative and antiapoptotic growth factor." (PMID 29259973, 2017). "In DM patients, insulin resistance leads to a compensatory increase in insulin secretion, and by inhibition of IGF binding proteins, this hyperinsulinemia may increase the biological activity of IGF-1, which is an antiapoptotic and mitogenic factor." (PMID 28423026, 2017). "Although the pathways by which the metabolic syndrome and its components increase cancer risk have not been fully elucidated, likely mechanisms involve insulin resistance, hyperinsulinemia, and elevated levels of insulin-like growth factor (IGF)-1, as well as increased levels of inflammation." (PMID 26300918, 2015). "Thus, the Ames fibroblasts are refractory to IGF-1 stimulated phosphorylation of Ser636/639 which could result in the reduced mTOR/S6K1 signaling, attenuation of protein synthesis and decreased insulin resistance." (PMID 26474286, 2015). "Another recent study found that sensitivity to T2D is gender dependent in mice with impaired IGF-1 actions, showing that without high fat diet feeding males tend to develop glucose intolerance with age along with insulin resistance, which occurred in both males and females." (PMID 26467524, 2015). "As NAFLD is related to insulin resistance, we hypothesized that, despite low IGF1, NAFLD would be absent or mild in this model." (PMID 25117570, 2014). "This suggests that IGF-1 could be both a pro-atherogenic and an anti-atherogenic factor indicating that IGFBP-3 levels and its regulation on IGF-1 may be a better indicator and marker of insulin resistance." (PMID 23383064, 2013). "In addition, a recent large prospective study has concluded the absence of correlation between the plasma IGF-1 level and insulin resistance." (PMID 24058525, 2013). "Most studies do not support an association of insulin resistance with %DBA or ADBA that is independent of adiposity, but growth hormone is the primary secretagogue for insulin-like growth factor-1, which is positively associated with %DBA and ADBA in premenopausal women." (PMID 22800711, 2012). "When insulin resistance occurs or IGF-1 is lacking, this pathway is inhibited." (PMID 21211055, 2011). "In the future, we will examine in all women recruited in the Diana-5 study how IGF-1 levels, insulin resistance, and fasting insulin levels in women without MetS may influence the incidence of relapses, secondary BC, and metastases compared to women diagnosed with MetS." (PMID 37106164, 2023). "In particular, it is well known that obesity is characterized by insulin resistance and low-grade systemic inflammation, which may affect the oncological outcomes of NMIBC patients as a result of insulin, insulin-like growth factor 1(IGF-1), cytokines, and growth factor effects." (PMID 33343662, 2020). "Therefore, it seems plausible that the presence of VAT, rather than GH/IGF-1 activation, could represent the main factor accounting for insulin resistance in patients with ACRO." (PMID 31561638, 2019).
Insulin resistance (continued). "In summary, parameters predicting treatment resistance in SZ patients were IGF-1, LDL, and age at disease onset; whereas glucose, insulin resistance, or sex did not affect the predictivity of treatment resistant." (PMID 40141202, 2025). "The increase in GH levels, without an accompanying increase in the levels of IGF-1, leads to an imbalance of the GH/IGF-1 axis, as it is an insulin resistance marker." (PMID 38136045, 2023). "In addition, the IGF-1 levels increased in rhGH treatment group, followed by the decrease of the liver enzyme and the improvements of the lipid profile, without significant effects on increased insulin resistance and negative effects on the glucose homeostasis." (PMID 29615058, 2018). "In Alzheimer’s, neurons can become both insulin- and IGF-1-resistant, even absent the clinical diagnosis of diabetes, with elevations in IRS-1 serving as a biomarker for brain insulin-resistance." (PMID 26823968, 2016). "Excessive adiposity‐induced insulin resistance and compensatory hyperinsulinemia have been shown to decrease hepatic synthesis of IGFBP‐1, which translates into increased concentrations of bioavailable IGF‐1, without modifications in serum total IGF‐1 levels." (PMID 26443692, 2016). "Since the IrP1195L/wt mice also showed insulin resistance, but not IGF-1 resistance, IGF-1 resistance might be necessary for the lifespan extension in mice." (PMID 21876806, 2011).